XIST (X inactive specific transcript)
Diseases named in the same sentence as XIST in open-access papers (continued):
Sharing a sentence is not in itself a finding about the gene and the disease.
cancer (continued). "For instance, the cancer-associated nuclear lncRNA MALAT-1 has been reported as a target of miR-9, while another cancer-associated nuclear lncRNA, XIST, has been reported as a target of miR-210." (PMID 38167929, 2024). "The current data also show that XIST serves primarily as a miRNA molecular sponge to regulate the expression of miRNA targets in male biased cancers." (PMID 39639337, 2024). "XIST was found to interact with miR-92b in hepatocellular carcinoma and inhibited cancer progression mediated by its direct target, Smad7." (PMID 39639337, 2024). "Despite previous studies demonstrating a link of aberrant XIST expression to inflammation and cancer stemness, the mechanisms involved remain elusive." (PMID 36922677, 2023). "Evidence accumulated suggested that XIST played critical regulatory roles in sex disparities diseases, such as autoimmune diseases, sex disparities cancers, neurological disorders and so on." (PMID 38148658, 2023). "XIST depletion or knock-out studies have revealed XIST-dependent genes in multiple tissue types, including cancer cells." (PMID 38131901, 2023). "This mutual regulation of XIST and STAT3 further supports a role of XIST in promoting cancer stemness." (PMID 36922677, 2023). "Two resistant probes located in the multiple transcription start sites (TSSs) of XIST were methylated in both female and male non-cancer tissues and in the HCT116 parental cells." (PMID 35654826, 2022). "Generally, XIST expression was positively related to about half of these markers in various cancers, such as CD2000, CD200R1, CD274, members of the tumor necrosis factor (TNF) ligand family, and so on." (PMID 36212008, 2022). "For example, in glioma, knocking down the expression of lncRNA XIST can upregulate the expression of miRNA miR-152, thereby inhibiting the proliferation, invasion, and migration of cancer cells and promoting apoptosis." (PMID 36457751, 2022). "XIST, a lncRNA, has been shown to promote the progression of various cancers through its high expression." (PMID 36531222, 2022). "Then, we analyzed the prognostic role of XIST across cancers in GEPIA2, Kaplan-Meier Plotter and PrognoScan." (PMID 36212008, 2022). "The expression levels of XIST seemed to be skimble-scamble in different types of human cancers in GEPIA2." (PMID 36212008, 2022). "Increasing pieces of evidence had revealed that lncRNA XIST played a vital role in many biological processes in human cancer." (PMID 35937995, 2022). "These axes initiated by XIST are involved in promoting cell proliferation, migration, and invasion of three different cancer types as shown in vitro." (PMID 36362406, 2022). "Then, we selected out 4 miRNAs, including miR-103a-3p, miR-107, miR-130b-3p and miR-96–5p, which were all negatively related to XIST expression in more than 3 types of cancers." (PMID 36212008, 2022). "For example, more cancer patients will be selected out and divided into groups by sub-types with 5-year or 10-year follow-up, so that we can confirm the prognostic roles both of expression and methylation of XIST in sub-types of cancers." (PMID 36212008, 2022). "In summary, abnormal expression of XIST influenced prognosis, miRNAs and immune infiltration across cancers, especially BRCA." (PMID 36212008, 2022). "Three databases, Oncomine, TIMER 2.0 and GEPIA2 displayed the transcription levels of XIST in various types of cancers." (PMID 36212008, 2022). "Several researches showed that growth and metastasis of cancer cells were facilitated due to the abnormal upregulation of XIST." (PMID 36212008, 2022). "In these cancers, XIST has been reported to serve as a carcinogenic driver that greatly promotes cancer cell proliferation, invasion, and migration." (PMID 35723009, 2022).
cancer (continued). "For instance, the detection of biological behaviors of cancer cells is insufficient; hence, more cellular functions should be examined to further determine the role of XIST." (PMID 35723009, 2022). "Particularly, expressions of ZFX and TXLNG were both positively correlated with XIST in over 10 cancers." (PMID 36212008, 2022). "The different studies mainly related the miRNA sponging activity of XIST to an oncogenic role in different types of cancer." (PMID 35054794, 2022). "The level of expression of XIST in NSCLC was also found to influence the cancer cells’ oxidative stress." (PMID 36077530, 2022). "On the whole, XIST was abnormally expressed in different cancers, especially in BRCA, OV, COAD and READ." (PMID 36212008, 2022). "Over 8 proteins were significantly related to XIST in 4 types of cancers, including BRCA, KIRC, OV and UCEC." (PMID 36212008, 2022). "This research comprehensively investigated XIST transcription across cancers from Oncomine, TIMER 2.0 and GEPIA2." (PMID 36212008, 2022). "Among them, TNRC6, DGCR8, C17ORF85, ZC3H7B, SFRS1 and TIA1, were obviously positively associated with XIST in ≥3 cancers; while eIF4AIII, FXR1, FXR2 and C22ORF28 were significantly negatively correlated with XIST in ≥3 cancers." (PMID 36212008, 2022). "XIST was one of the first lncRNAs to be discovered in the 1990s and participates in the regulation of many cancer-related processes and the inflammatory response." (PMID 34512861, 2021). "In subsequent experiments, we further observed that miR-191-5p partly eliminated the cancer-promoting effect of XIST in RB cells." (PMID 33942699, 2021). "More and more scholarly evidence has shown that XIST is dysregulated in many cancers and inflammatory conditions." (PMID 33777260, 2021). "Emerging evidence suggests that XIST participates in regulating inflammation, tissue injury, and cancer." (PMID 34512861, 2021). "Firstly, XIST deletion from hematopoietic progenitors results in aberrant proliferative growth, consistent with myelodysplasia [now recognised as cancer]." (PMID 33664771, 2021). "It is reported that the m6A writer METTL14 methylated and down-regulated lncRNA XIST in cancer cells." (PMID 34395433, 2021). "The first two reported ceRNAs of miR-34a are TUG1 lncRNA and XIST lncRNA, which function as miR-34a sponges and promote tumorigenesis and cancer progression by increasing cell proliferation and angiogenesis." (PMID 33763422, 2021). "Over-expression of lncRNA XIST induces autophagy, which is a protective mechanism engaged by cancer cells that ensures survival; as such, elevated XIST has been linked with poor cisplatin response." (PMID 33803619, 2021). "Our findings have suggested that CuB exerts its anti-cancer effects by regulating XIST and miR-29b expression in TSCC." (PMID 34295808, 2021). "Ranked No. 2 is XIST, and the research in the literature shows that XIST plays an important regulatory role in cancer biology." (PMID 33794766, 2021). "Together, these results suggest that CuB exerts significant anti-cancer activity by regulating expression of XIST via miR-29b." (PMID 34295808, 2021). "The lncRNAs XIST, TTN-AS1, STRA6LP, and TSIX had high numbers of mutations in most cancers, which play an important role in the oncogenic mechanism." (PMID 34079798, 2021). "Its function as a ceRNA is one of the most common mechanisms by which XIST contributes to cancer promotion." (PMID 34771549, 2021). "Nevertheless, evidence suggests that the Xi epigenetic status and XIST expression levels are potential cancer biomarkers as a readout for genomic instability or epigenomic changes." (PMID 33916248, 2021).
cancer (continued). "It has been shown that high expression of this lncRNA is related to poor clinical outcome in different cancers, but in another study, authors demonstrate that high XIST expression is related to an increased brain metastasis–free survival in BRCA patients." (PMID 33912452, 2021). "Gene ontology (GO) and KEGG (Kyoto Encyclopedia of Genes and Genomes) pathway enrichment analyses demonstrated that XIST participated in various cancer-related functions, including cell proliferation and metastasis." (PMID 34733782, 2021). "In line with in vitro studies, abnormal expression of XIST affects tumorigenesis in animal models of cancer." (PMID 34179019, 2021). "Abnormal expression of XIST has been seen in various human cancers, where it plays a pathological function." (PMID 33980320, 2021). "Secondly, when XIST is selectively deleted from the gut epithelium and carcinogenic stimuli administered, cancer develops." (PMID 33664771, 2021). "Almost all studies have indicated that up-regulation of XIST enhances tumorigenic ability of cancer cells, while its silencing has the opposite effects." (PMID 34179019, 2021). "The X-inactive-specific transcript (XIST) lncRNA, produced by the XIST gene, is a critical regulator of cancer, levels of which correlate with cell differentiation, proliferation, and genome maintenance." (PMID 33980320, 2021). "Since the cancer-promoting effects of BDNF in RB are confirmed by previous studies, we concluded that XIST exerted its cancer-promoting effect partly by up-regulating the expression of BDNF." (PMID 33942699, 2021). "Most studies to date focused on the function of XIST in human cancers, i.e. colorectal cancer, uveal NSCLC, hepatocellular carcinoma, and breast cancer." (PMID 32209729, 2020). "XIST has been reported to be involved in the biological processes of cancer cells, and it is resistant to chemo- and radiotherapies." (PMID 33364236, 2020). "Some SE‐associated ce‐lncRNAs with high degree/betweenness were highly associated with cancer hallmarks, including lncRNAs reported in cancer (e.g., NEAT1, HOTAIR, XIST, and SNHG5)." (PMID 32460441, 2020). "In fact, some lncRNAs including XIST have been reported to show either suppress or promote cancer depending on the type of cancer." (PMID 32684827, 2020). "Overall, similar to previously published results where XIST is upregulated in various cancers, we found a similar trend, in LUAD compared to normal lung cohort (LUNG), whereas in LUSC a downregulation was observed." (PMID 33255394, 2020). "XIST has been reported to be aberrantly expressed and closely related to the progression of various cancers." (PMID 32127028, 2020). "XIST expression has been reported to contribute to the resistance to chemotherapeutic drugs in various types of cancers." (PMID 32209729, 2020). "XIST seems to play a potential role as a novel predictor of human cancer prognosis and presents an abnormal expression in various types of cancer." (PMID 33371204, 2020). "XIST is known for promoting cancer proliferation and migration, however only the Chungbuk cohort showed a correlation with unfavorable DSS (p = 0.0044)." (PMID 33235218, 2020). "More and more research indicates that lncRNA XIST plays an important role in cell proliferation and differentiation, and it is dysregulated in many cancers." (PMID 32038997, 2019). "Many of these studies contemplated the involvement of XIST in protecting cancer-related genes from miRNA-mediated negative regulation." (PMID 31419261, 2019). "Pseudouridylation has also been found in lncRNAs correlated with cancer, such as XIST and MALAT1, as previously discussed." (PMID 30654440, 2019). "In harmony with our results, lncRNA XIST was proven to be upregulated in different types of cancer tissues compared to healthy tissues." (PMID 31998636, 2019). "Up to now, XIST was certificated to participate in the migration, growth and invasion of cancer cells and influenced the occurrence as well as development of cancers." (PMID 30858762, 2019).
cancer (continued). "Reportedly, XIST participates in the proliferation, apoptosis, invasion, migration and resistance to chemo- and radio-therapies of cancer cells." (PMID 30463570, 2018). "Seven of the nine studies reported the expression level of XIST was up-regulated in cancer tissues and cell lines, 2 studies reported it was down-regulated." (PMID 29568404, 2018). "The result showed that higher lncRNA XIST expression in cancer tissue was related to a worse overall survival (OS) (HR = 1.54, 95% CI 1.07–2.23)." (PMID 29556138, 2018). "In order to combine the results of former studies about XIST and cancers, we elucidated the relationship between XIST expression levels and prognosis and also clinicopathological characteristics in cancer patients in the present meta-analysis." (PMID 29752340, 2018). "In conclusion, the pooled results in our current work suggest that XIST is an important prognostic biomarker in cancer patients." (PMID 29568404, 2018). "It played an important role in proliferation, migration and invasion in cancer cells in vitro and in vivo, which indicated that XIST exerted an essential role on the occurrence and development of various tumors." (PMID 29556138, 2018). "Among cancer patients with XIST as the oncogenes, digestive system carcinoma patients were more closely associated with shorter OS than non-digestive system carcinoma patients." (PMID 29568404, 2018). "Loss of X-chromosome inactivation and abnormal expression of XIST are commonly observed in various cancers." (PMID 29752340, 2018). "It was reported that the high expression of lncRNA XIST was a risk factor for the prognosis of cancers, while some reports indicated that the high expression of lncRNA XIST was a beneficial factor in the prognosis of cancers." (PMID 29556138, 2018). "As we mentioned, XIST exerts its biological effects in cancers commonly through interacting with different miRNAs." (PMID 30463570, 2018). "We then detected expression of XIST in a panel of ESCC cancer cells including KYSE30, KYSE510, KYSE410, KYSE520, KYSE140 and KYSE150 and one immortalized normal epithelial cells (NE1)." (PMID 29100288, 2017). "Our data indicated that XIST was significantly upregulated in esophageal squamous cancerous tissues and cancer cell lines, as compared with that in the corresponding non-cancerous tissues and immortalized normal squamous epithelial cells." (PMID 29100288, 2017). "Among the large amount of lncRNAs, XIST has been reported to be specifically upregulated in cancers, and promote cancer cell proliferation." (PMID 29029436, 2017). "NONHSAT102729 and NONHSAT078790 were the core lncRNAs in TF-lncRNA network (n335563 and n340532 respectively), and XIST has been extensively studied in other cancers and it is also downregulated in DLBCL cell lines to certain extent." (PMID 28423571, 2017). "Significant upregulation of XIST in cancer tissues prompted us to investigate its roles on aggressive phenotypes of ESCC cells." (PMID 29100288, 2017). "To determine the role of lncRNA XIST in different cancers, we explored the expression of XIST in the TCGA data portal from Starbase ver2.0." (PMID 29212233, 2017). "Cancer cells have shown either downregulation or upregulation of XIST, suggesting its complex and controversial role in cancer biology." (PMID 27608009, 2016). "Expression of XIST is lost is these cancers resulting in extra active X chromosomes in both male and female patients of non-Hodgkin lymphoma." (PMID 26082843, 2015). "In fact the aberrant expression of XIST results not only in aberrant ploidy of X chromosomes but also in the increased resistance of cancer cells to chemotherapy." (PMID 26082843, 2015). "Atractylenolide II and Platycodin D, which are apoptosis inducers used in Chinese and East Asian traditional medicine to treat cancers, showed inhibitory activity on XIST expression and reversed the inhibitory effects of XIST on miR-30a-5p and miR-335, respectively." (PMID 41601966, 2026).
cancer (continued). "It has been documented that the overexpression of XIST in cancer cells may increase cancer invasion and metastasis." (PMID 40028475, 2025). "In well-differentiated cells such as human cancer cells and mouse fibroblasts, XIST/Xist deletion leads to downregulation of the X chromosome compared to autosomes, suggesting XCI-independent transcriptional changes after XIST/Xist loss." (PMID 40981384, 2025). "This MUC1-C/XIST pathway should, in principle, be reversible with resolution of inflammation; however, if irreversibly established in cancer progression, represents a mechanistic explanation for the upregulation of XIST in pan-cancers." (PMID 38740827, 2024). "XIST is upregulated in male and female cancers by unclear mechanisms." (PMID 38740827, 2024). "The potential involvement of XIST in contributing to intrinsic chronic inflammation in cancer progression also remains unclear." (PMID 38740827, 2024). "Here, we sought to understand how MUC1-C increases XIST levels in cancer cells." (PMID 38740827, 2024). "MUC1-C and XIST are dysregulated in chronic inflammation and cancer." (PMID 38740827, 2024). "While XIST downregulation is associated with cancer treatment resistance, it remains unclear whether XIST downregulation occurs early or late in cancer development, or even after cancer treatment." (PMID 39546568, 2024). "Cancer cells that lose XIST expression become less differentiated and more plastic, allowing them to adapt more easily to their environment, which may contribute to cancer progression." (PMID 39546568, 2024). "XIST is aberrantly upregulated in diverse human cancers from both sexes by unclear mechanisms." (PMID 38740827, 2024). "The results indicate that XIST KD promotes SC and progenitor-like cell populations and may possibly enhance cancer cellular plasticity coping with stressful conditions such as hypoxia." (PMID 39546568, 2024). "XIST is a critical regulator in X chromosome inactivation (hence the name), but it has also been shown to be involved in many biological and pathological processes, including cancer, inflammation, and cardiac and neurological diseases." (PMID 38265097, 2024). "For instance, m6A lncRNA MALAT1 could regulate metastasis to control cancer cell proliferation, migration, and apoptosis in many cancers; lncRNA XIST bearing m6A and m5C modifications may act as a tumor suppressor or oncogene in colorectal cancer and leukemia." (PMID 37158958, 2023). "SRC-1 acted as an oncogene and promoted the stability of XIST RNA in cancer cells." (PMID 36903477, 2023). "Abnormal XIST expression plays a vital role in the occurrence and development of many cancers." (PMID 37504269, 2023). "However, a few of them—including XIST—were found to synergistically influence cancer pathways in multiple tumor contexts together with other lncRNAs." (PMID 37444543, 2023). "Exosomal lncRNA like MALAT1, growth arrest-specific 5 (GAS5), H19, HOTAIR, small ubiquitin-like modifier 1 SUMO1 pseudogene 3 (SUMO1P3) and X-inactive specific transcript (XIST) were previously shown upregulated in the blood, lung and breast tissues of cancer patients." (PMID 37153158, 2023). "In addition, XIST expression was positively related to more than 20 immune checkpoint markers and over 10 immune cell types across cancers." (PMID 36212008, 2022). "One study reported that XIST promotes the migration and invasion of PTC cells by sponging miR-101-3p, which, in turn, targets the CLDN1 gene that codes for claudin-1, a tight junction protein associated with cancer cell migration and invasion." (PMID 35804851, 2022). "The contradictory roles of XIST in diverse cancers may be attributed to the differences in tissue sources, extracellular microenvironment, and regulatory factors." (PMID 35723009, 2022).